CLPB (ClpB family mitochondrial disaggregase)
Diseases named in the same sentence as CLPB in open-access papers (continued):
Sharing a sentence is not in itself a finding about the gene and the disease.
neurodegenerative disease (2 papers, 2020 to 2026). A disorder of the central nervous system characterized by gradual and progressive loss of neural tissue and neurologic function. "We next examined whether ClpB could facilitate the aggregation of proteins involved in the pathologies of other neurodegenerative diseases, such as AD, PD, and FTD." (PMID 41424860, 2026). "Since ClpB was previously established as a disaggregase 16, 37, we hypothesized that neuronal ClpB might modulate various protein aggregates observed in neurodegenerative diseases." (PMID 41424860, 2026). "By linking ClpB to the broader context of aging-related proteostasis collapse and mitochondrial quality control, our work provides a mechanistic framework that holds significant implications for therapeutic strategies across a range of neurodegenerative diseases." (PMID 41424860, 2026). "To this end, we transfected plasmids expressing EGFP-α-synuclein, EGFP-parkin, EGFP-Tau, or EGFP-TDP43 (as a proxy for each neurodegenerative disease) into control or CLPB-KO HEK293T cells, or co-transfected them along with the CLPB expression vector." (PMID 41424860, 2026).
infectious disease (1 paper, 2021). A disorder directly resulting from the presence and activity of a microbial, viral, or parasitic agent in humans. "This review focuses on the molecular chaperone ClpB that belongs to the Hsp100/Clp subfamily of the AAA+ ATPases and its biological function in selected bacterial pathogens, causing a variety of human infectious diseases, including zoonoses." (PMID 34070174, 2021).
metabolic disease (1 paper, 2023). A congenital disorder (due to inherited enzyme abnormality) or acquired (due to failure of a metabolically important organ) disorder resulting from an abnormal metabolic process. "Finally, we found that the enterobacterial ClpB protein, as well as its known satietogenic action, has the additional beneficial effect of increasing glucose tolerance, which can be exploited for the prevention of metabolic diseases." (PMID 37445766, 2023).
CLPB also shares sentences with these, for which no sentence is quoted: cataract (4 papers); 3-methylglutaconic aciduria (3); cancer (3); diabetes (3); epilepsy (2); tumor (2); and autonomic neuropathy (1); atrial fibrillation and flutter (1); atrial septal defect (1); colorectal cancer (1); Cyclic neutropenia (1); deafness (1); depression (1); Dravet syndrome (1); dysautonomia (1); febrile convulsions (1); Huntington disease (1); Infertility (1); intellectual disability syndrome (1); lactic acidosis (1); leukemia (1); leukodystrophy (1); malignant mesothelioma (1); movement disorder (1); nail infection (1); neurological disorders (1); non-melanoma skin carcinoma (1); optic atrophy (1); Parkinson disease (1); premature ovarian failure (1).
A further 4 diseases each share a sentence with CLPB in 1 paper.